NRSN1 (neurensin 1)
Description:
May play an important role in neural organelle transport, and in transduction of nerve signals or in nerve growth. May play a role in neurite extension. May play a role in memory consolidation (By similarity).
Synonyms: VMP; p24
Tractability: Antibody: UniProt predicts a signal peptide or a membrane-spanning region; the Human Protein Atlas places it where antibodies can reach.
Gene: Protein-coding gene on chromosome 6 (24,126,154 to 24,154,900, forward strand). Ensembl gene ENSG00000152954.
Subcellular location: Membrane; Cell projection, neuron projection
Subcellular location (Human Protein Atlas): Cytosol; Plasma membrane
Gene Ontology:
Molecular function: protein binding
Biological process: nervous system development
Cellular component: cytoplasmic vesicle; growth cone; neuron projection; neuronal cell body; transport vesicle; membrane
Genetic constraint (gnomAD): Loss-of-function variants: 14 observed, 18.28 expected, observed/expected ratio (o/e) 0.77, 90% interval 0.5 to 1.2. The upper end of that interval is the gene's LOEUF score, 1.2, which puts it in group 5 of 6, group 1 being the genes least tolerant of losing a copy. Missense variants: 209 observed, 246.46 expected, observed/expected ratio (o/e) 0.85, 90% interval 0.76 to 0.95. Synonymous variants: 79 observed, 99.42 expected, observed/expected ratio (o/e) 0.79, 90% interval 0.66 to 0.96.
Homologues: Orthologues: chimpanzee NRSN1 (100% identical), macaque NRSN1 (98% identical), rabbit NRSN1 (94% identical), guinea pig NRSN1 (92% identical), mouse Nrsn1 (92% identical), pig NRSN1 (92% identical), rat Nrsn1 (92% identical), dog NRSN1 (85% identical), tropical clawed frog nrsn1 (77% identical), zebrafish nrsn1 (61% identical), zebrafish nrsn1l (40% identical). Paralogues in human: NRSN2 (32% identical).
Diseases named in the same sentence as NRSN1 in open-access papers:
NRSN1 is named in the same sentence as 10 diseases in open-access papers, as found by Europe PMC text mining. Sharing a sentence is not in itself a finding about the gene and the disease. The quoted sentences say what the papers report.
glioma (2 papers, 2020 to 2022). A benign or malignant brain and spinal cord tumor that arises from glial cells (astrocytes, oligodendrocytes, ependymal cells). "Most of them were reported in glioma, CACNG2 JPH3, TUBB6, NRSN1, FAM19A2, NALCN, GNAL have not been reported yet." (PMID 32406502, 2020). "CACNG2, JPH3, TUBB6, NRSN1, FAM19A2, NALCN, GNAL have not been reported in gliomas." (PMID 32406502, 2020). "In addition, there is no report about CACNG2, JPH3, TUBB6 (tubulin β 6 class V), NRSN1, FAM19A2, NALCN, CDH18, GNAL on glioma." (PMID 32406502, 2020). "In addition, CACNG2, JPH3, TUBB6, NRSN1, FAM19A2, NALCN, GNAL were not reported in glioma." (PMID 32406502, 2020).
Hirschsprung disease (2 papers, 2018 to 2020). Hirschsprung disease (HSCR) is a congenital intestinal motility disorder that is characterized by signs of intestinal obstruction due to the presence of an aganglionic segment of variable extent in the terminal part of the colon. "In a recent study, we have shown that genetic markers within GAL, GAP43 and NRSN1 contribute to the altered HSCR susceptibility, and importantly, the interaction networks among GAP43, NRSN1 and PTCH1 confer an increased risk to Hirschsprung disease." (PMID 32139661, 2020).
autism spectrum disorder (1 paper, 2022). A spectrum of developmental disorders that includes autism, and Asperger syndrome. "MR analysis showed that NRSN1 is a protective factor against autism spectrum disorders and eczema, and that ADCYAP1 is protective against oropharyngeal cancer." (PMID 35602164, 2022).
Obesity (1 paper, 2023). Accumulation of substantial excess body fat. "The RNA seq gene signature include Neurensin 1 (Nrsn1) and Leucine rich repeat neuronal 1 (Lrrn1) in which polymorphisms in these gene have been linked to changes in food intake and obesity." (PMID 37604246, 2023).
retinal degeneration (1 paper, 2017). Degeneration of the retina. "They include genes involved in nuclear trafficking and gene silencing (IPO8), fast axonal guidance and synaptic specificity (PCDH12), transduction of nerve signals (NRSN1), retinal degeneration (LMO7), synaptic glutamate release (SH3GL2), and broader nervous system development and function." (PMID 29064472, 2017).
NRSN1 also shares sentences with these, for which no sentence is quoted: dyslexia (3 papers); eczema (1); infection (1); oropharyngeal cancer (1); tumor (1).